ALB (albumin)
Diseases named in the same sentence as ALB in open-access papers (continued):
Sharing a sentence is not in itself a finding about the gene and the disease.
diabetes (continued). "Specifically, those with CKD caused by hypertension or diabetes frequently have severe vascular damage and fluid management issues, which can be exacerbated by albumin administration, leading to a deterioration in their overall clinical condition." (PMID 39434907, 2024). "Among those with type 2 diabetes mellitus, urinary albumin excretion > 30 mg/24 h was also linked to worse timed chair rise stand test time and lower maximal grip strength." (PMID 38594601, 2024). "Glycation affects a number of plasma proteins including albumin, haptoglobin and fibrinogen and is associated with microvascular damage and organ dysfunction in advanced diabetes." (PMID 38741158, 2024). "Only a few long-term clinical trials evaluated the relationship between glycated albumin and the risk of chronic complications of diabetes." (PMID 39684653, 2024). "This study established a model encompassing ADL, NIHSS scores, diabetes, BMI, grip strength, serum albumin levels, and depression to forecast the nutritional risk in frail older stroke patients." (PMID 38761298, 2024). "Lastly, the prescription of VDRA therapy was associated with a history of diabetes, baseline iPTH > 150 ng/l, serum albumin > 35 g/l, and abnormal calcium levels (≥ 2.6 mmol/L)." (PMID 38378456, 2024). "Low serum albumin levels are associated with poor nutritional status, chronic inflammation, and increased risk of complications in diabetes." (PMID 39125606, 2024). "A study has confirmed the significant association between serum 25(OH)D level with age, diabetes mellitus, albumin level, and creatinine level." (PMID 38652006, 2024). "We found that all-cause mortality was associated with age, diabetes, a low concentration of albumin, and high levels of OPG and hs-CRP; Bsm1 polymorphism was not significant." (PMID 39335504, 2024). "Multiple analysis data showed that sex, diabetes, albumin level, and NLR were independently associated with serum 25(OH)D level (p = .0121, p = .015, p = .033, and p = .041, respectively)." (PMID 38652006, 2024). "Diabetic kidney disease (DKD) represents a severe and common complication associated with diabetes, marked by increased levels of albumin in the urine and a gradual decline in kidney function due to the death of tubular cells." (PMID 38465879, 2024). "When intragroup comparison was done, there was statistical significance observed for total protein, albumin, globulin, and microprotein, also suggesting the reduced burden of the complications associated with diabetes." (PMID 37809241, 2023). "Death was associated with lower albumin levels and older age, while peritonitis was associated with diabetes." (PMID 35788617, 2023). "The nomogram comprised independent risk factors, including age, diabetes, platelet–lymphocyte ratio, leukoencephalopathy, neutrophil, monocytes, total protein, platelet, albumin, indirect bilirubin, and high-density lipoprotein." (PMID 37508983, 2023). "Both age (per each year), serum creatinine, albumin blood concentration, presence of arterial hypertension, and diabetes mellitus were demonstrated as independent risk factors of shortened survival." (PMID 38201601, 2023). "In the present study, we observed that patients undergoing hemodialysis with a higher risk of mortality exhibited a greater prevalence of diabetes mellitus, older age, elevated serum endocan levels, and lower serum creatinine and albumin levels." (PMID 38068479, 2023). "IgA concentration and poly-IgR expression in the SGs were associated with serum albumin concentration, heart rate, blood pressure, and blood glucose levels, indicative of diabetes pathology." (PMID 37109747, 2023). "A seven-item index (mIFG) was developed using variables associated with frailty, cachexia, and sarcopenia, drawn from the literature (weight loss, low body mass index, dyspnea, diabetes, serum albumin, hematocrit, and creatinine)." (PMID 36703217, 2023).
diabetes (continued). "Rare genetic variants in the CUBN gene encoding the main albumin-transporter in the proximal tubule of the kidneys have previously been associated with microalbuminuria and higher urine albumin levels, also in diabetes." (PMID 36926036, 2023). "The National Kidney Foundation, the American Diabetes Association, and the National Institutes of Health advocate the estimation of albumin in the urine by the method of albumin: creatinine ratio." (PMID 37065365, 2023). "In conclusion, this study sheds light on the crucial role of urine albumin estimation as an early diagnostic tool for diabetic nephropathy within the context of diabetes mellitus patients at a central India tertiary care hospital." (PMID 37868453, 2023). "Univariate analysis showed that diabetes, older age, shorter time free of infection and comorbidities, and lower levels of albumin and hemoglobin would be associated with death in the dialysis population." (PMID 35510838, 2023). "Cox regression analysis found that diabetes mellitus was associated with peritonitis, while age and albumin level on admission were predictors of death." (PMID 35788617, 2023). "And serum albumin, the major circulating protein in blood, is glycosylated in patients with diabetes due to an underlying modification factor that contributes to the alteration of albumin’s multitude of functions and the patients’ diabetic state." (PMID 38203654, 2023). "Hemodialysis patients with diabetes mellitus, older age, higher serum endocan, and lower creatinine and albumin levels had a higher risk of mortality." (PMID 38068479, 2023). "Our recent study further suggests that the effect of some of these variants on urine albumin levels is 2-3 times higher in diabetes compared to non-diabetes." (PMID 36926036, 2023). "In a previous study, multivariate analysis showed that age, male sex, diabetes, platelet count, gamma‐glutamyltransferase and albumin levels, and the 7‐SNP genetic risk score, including PNPLA3 and HSD17B13, are independent risk factors of HCC development." (PMID 37644826, 2023). "Significantly higher risks of CV-MACE, CVM, and all other individual CV and mortality outcomes were associated with increasing age, a 5 g/L serum albumin decrease, and history of diabetes or CVD." (PMID 37289366, 2023). "The patients on HD with a 3-month mean albumin level of < 3.5 g/dL were older, had a higher prevalence of diabetes mellitus and heart failure, and a higher risk of mortality." (PMID 37095523, 2023). "For example, the authors found that increased serum levels of the C-reactive protein/albumin rate have been associated with renal damage in diabetics with nephropathy in the CARE TIME study." (PMID 37370958, 2023). "The incidence of AL after gastrectomy is associated with low albumin concentration, diabetes, the laparoscopic method, and extent of resection." (PMID 37007118, 2023). "The incidence of stroke increases over time, and the closely associated risk factors are diabetes and low albumin level." (PMID 37848510, 2023). "In the subgroup analysis of participants with diabetes, hypertension or dyslipidemia, there were positive associations between serum zinc levels with serum albumin and homocysteine (p < 0.05)." (PMID 36678192, 2023). "In line with our observations, several reports have indicated that flavonoids ameliorate diabetes-induced renal albumin loss." (PMID 36771740, 2023). "The other admission variables associated with the risk of death found in the presentstudy were age, diabetes, initiation of HD in a hospital, body mass index,transferrin saturation index, hemoglobin, albumin and alkaline phosphatase levelsand fluid overload." (PMID 36662571, 2023). "Multivariate analysis showed that diabetes and serum albumin levels were independent risk factors for intracranial atherosclerosis (P< 0.05)." (PMID 37210474, 2023).
diabetes (continued). "Multivariate logistic analysis showed that increased APACHE II score, lower ALB, diabetes, high PCT were independent risk factors for septic shock." (PMID 37626308, 2023). "We have observed that diabetes is associated with increased urinary excretion of total protein and albumin." (PMID 37834118, 2023). "The survival of patients on HD and PD is similar, and the risk factors associated with lower survival are older age, having diabetes, lower levels of albumin and hemoglobin at the beginning of therapy." (PMID 35510838, 2023). "to assess the associations between SDNN and HbA1c, diabetes duration, systolic blood pressure, as well as any sustained albumin excretion rate (AER) ≥ 30 mg/day in T1DM patients." (PMID 37854193, 2023). "The incidence of stroke increases over time, and the associated risk factors include diabetes and low albumin levels." (PMID 37848510, 2023). "Univariate analysis showed that age, diabetes, and serum albumin level were risk factors for intracranial atherosclerosis (P < .05)." (PMID 37210474, 2023). "Increasing age, albumin reduction, and prior history of diabetes or cardiovascular disease were risk factors for all outcomes except renal replacement therapy." (PMID 37289366, 2023). "The baseline characteristics between treatment arms were well-balanced for characteristics associated with an increased risk of DR, including duration of diabetes, glycaemic control, blood pressure, urinary albumin:creatinine ratio and smoking status." (PMID 37745288, 2023). "Older age at the time of dialysis initiation, the presence of diabetes, cardiovascular comorbidities, moderate to severe chronic liver disease, and lower level of serum albumin were independent risk factors for all-cause mortality in both females and males." (PMID 36329070, 2022). "A potential mechanism underlying reduced albumin endocytosis by PTCs in patients with diabetes was identified in cultured LLCPK cells as a reduction in megalin function induced by high glucose." (PMID 35378997, 2022). "Univariate ordinal logistic regression analysis showed that sex, diabetes mellitus, postoperative hemoglobin, and postoperative serum albumin were all risk factors for the severity of different postoperative Clavien–Dindo complications." (PMID 35187165, 2022). "Previous studies demonstrated that serum albumin was associated with many diseases such as diabetes and metabolic syndrome." (PMID 35284431, 2022). "Univariate Cox regression analysis revealed that age, the presence of diabetes mellitus, HBeAg positivity, lower platelet counts, lower serum albumin levels, and greater LS values were significantly associated with HCC development." (PMID 36611295, 2022). "In the data derived from the NHANES I population-based sample aged 55–74 years, diabetes was associated with an almost double risk of having a serum albumin concentration < 38 g/L." (PMID 35831938, 2022). "There were 28 lipids moleculars including 5 classes (Cers, LPCS, PCs, SMs, TG-FAs) that were associated with albumin after adjustment for sex, age, hypertension, diabetes, creatinine, uric acid, and 24hpro." (PMID 36224633, 2022). "We evaluated the association of glycated albumin (GA) and GA/HbA1c ratio with progression of COVID-19 from mild to severe disease in patients with type 2 diabetes mellitus (T2DM)." (PMID 35566453, 2022). "Among the eight variables (age, gender, medication therapy for diabetes, smoking, alcohol drinking, body mass index, hemoglobin A1c and urinary albumin) tested, smoking showed the strongest association with urinary pteridines." (PMID 35242903, 2022). "The association of diabetes mellitus, serum creatinine, albumin, CRP, GNRI, and CI levels with CV mortality continued in age and sex-adjusted multivariate models (Table-2)." (PMID 36326327, 2022).
diabetes (continued). "Multivariate analysis indicated that increased BMI, prolonged dialysis duration, warfarin therapy, hyperparathyroidism, diabetes, tumors, low serum albumin and high serum alkaline phosphatase levels were high-risk factors for calciphylaxis." (PMID 35755071, 2022). "Univariate analysis showed that age, GCS score, state of consciousness, diabetes, albumin, and computed tomography (CT) midline shift were associated with the risk of death from a DOC." (PMID 35875805, 2022). "Studies on the association between urinary albumin-to-creatinine ratio (uACR) and diabetes are limited." (PMID 36175972, 2022). "The estimated glomerular filtration rate (eGFR) and the albumin-to-creatinine ratio (ACR) are risk factors for diabetes-related outcomes." (PMID 35996147, 2022). "It has been demonstrated that glycated albumin (GA) is significantly associated with diabetes complications and mortality." (PMID 35045846, 2022). "A diabetes control and complications Trial found PTGDS (prostaglandin-H2 D-isomerase), strongly and positively associated with the albumin excretion rate in Type 1 Diabetes Mellitus." (PMID 36064366, 2022). "Following the publication of previous research, it was revealed that serum albumin was substantially related to diabetes, and this association remained significant even after correcting for other covariates." (PMID 35709212, 2022). "Second, data were not available for some possible confounders, such as residual kidney function, diabetes status, and serum albumin levels, but it is known that diabetes and hypoalbuminemia are associated with mortality in patients with AKI." (PMID 36407492, 2022). "After adjusting for age, sex, body mass index, duration of known diabetes, and urine albumin-to-creatinine ratio, HbA1c remained a significant risk factor for elevated urine NAG." (PMID 35743910, 2022). "Age, diabetes, history of CV disease, as well as a low serum albumin or an elevated hs-CRP were also significantly associated with MACE in the models." (PMID 34170371, 2022). "We also found that the following covariates were associated with CV mortality: age, ESRD due to diabetes, glomerulonephritis, and hypertension, albumin, Kt/V, alkaline phosphatase, and sodium in univariate analysis with Cox regression." (PMID 34979958, 2022). "A lot of research pointed out that TG/HDL-C was favorable to identify increased urinary albumin-to-creatinine ratio, insulin resistance, diabetes risk, incident hypertension, and cardiovascular events." (PMID 36263299, 2022). "•Usual predictors, such as diabetes, albumin and FIB-4 were associated with higher risk of a first liver event." (PMID 36061511, 2022). "A low serum albumin and chronic inflammation in type 2 diabetes mellitus caused muscle weakness and atrophy." (PMID 35290727, 2022). "Age, D-dimer, C-reactive protein, sequential organ failure assessment score and body temperature, decreasing albumin, and a history of diabetes were regarded as the major risk factors for COVID-19 severity." (PMID 36619998, 2022). "In univariate cox regression models, CV-mortality was associated with age, diabetes mellitus, serum creatinine, albumin, total cholesterol, LDL-cholesterol, triglycerides, CRP, GNRI, and CI." (PMID 36326327, 2022). "Multivariate logistic regression analysis showed that prolonged ICU stay (>60 days) after burn surgery was significantly associated with RDW/albumin ratio at postoperative day 1, age, diabetes mellitus and inhalation injury." (PMID 35097135, 2022). "The associations of low serum albumin level and diabetes with ESRD were also significantly positive (crude, Model 1, and Model 2) after adjusting for all variables in a categorical manner." (PMID 35893916, 2022). "In multivariate models adjusted for age, sex, systolic blood pressure and diabetes mellitus, total and free concentrations of pCS and pCG and albumin were significantly associated with the primary outcome of fatal or non-fatal CVEs, whereas prealbumin was not." (PMID 36013188, 2022).
diabetes (continued). "Among both cohorts, the HCC risk prediction models incorporated age, sex, diabetes, body mass index, platelet count, serum albumin and transaminases as cancer predictors." (PMID 34977518, 2022). "In conclusion, albumin levels on admission can predict <30 days in-hospital all-cause mortality independently of age, hypertension, dyslipidemia, diabetes mellitus, COPD, active cancer and glucose levels on hospital admission." (PMID 35160039, 2022). "Preoperative low protein, operative stage ≥ 3, a relatively large amount of intraoperative blood loss, old age and history of diabetes were independent predictors of albumin infusion after PLIF." (PMID 34717707, 2021). "Originally, albumin is an FA transport protein, and hyperfiltration in diabetes causes a high concentration of FAs to enter the tubular space, along with albumin." (PMID 33622285, 2021). "Elderly (age > 70 years), body mass index > 30, smoking, diabetes mellitus, coronary artery disease, chronic obstructive pulmonary disease, anemia, low serum albumin, operation time > 3h, and perioperative blood loss > 500 ml were recorded in this study." (PMID 34243798, 2021). "Supporting these findings, diabetes‐associated metabolites (high glucose and glycated albumin) were used to mimic the diabetic milieu in monocytes from healthy individuals and were found to increase NLRP1 expression." (PMID 33682108, 2021). "In univariate analysis, microvascular invasion (MVI), radiological capsule appearance on the computed tomography, chronic hepatitis B, diabetes mellitus and serum albumin, MVI were significantly associated with tumor necrosis by TACE (P < .02)." (PMID 34232206, 2021). "They found that high CRP (OR = 1.16, p = 0.033) and low albumin (OR = 0.91, p = 0.030) were risk factors for poor prognosis in patients with diabetes and COVID-19." (PMID 34164413, 2021). "Low albumin levels are associated with inflammation and are often found in difficult-to-heal diabetes-associated wounds." (PMID 33585030, 2021). "It was found that lower TGF-β1 mRNA levels were associated with older age of diabetes onset and higher urinary albumin excretion rate." (PMID 32936764, 2021). "Other measures of glycaemic control, namely fructosamine albumin, which are both glycated proteins but early advanced glycation adducts, were elevated with diabetes to a greater degree in high risk individuals." (PMID 33941808, 2021). "Most of the studies on serum ALB redox state have been conducted in its association with major oxidative stress-related diseases such as liver diseases, renal failures, and diabetes mellitus." (PMID 33804859, 2021). "Magnesium and albumin are examples of several factors that have been suggested to play a role in increased platelet activity and trombotic risk in diabetes." (PMID 34078390, 2021). "Preoperative serum albumin <3.5 g/dL, BMI ≥40 kg/m2, tobacco use, and diabetes are associated with increased risk of postoperative infection, readmission, any complication, and mortality after primary THA." (PMID 34277906, 2021). "Increased susceptibility of platelet activation in diabetes has been suggested in several studies, but albumin is rarely mentioned." (PMID 34078390, 2021). "Preoperative low level of protein, operative stage ≥ 3, severe intraoperative blood loss, old age and history of diabetes were independent predictors of albumin infusion in the postoperative period of PLIF." (PMID 34717707, 2021). "Diabetic nephropathy is a complication of diabetes mellitus (DM) characterized by high levels of urine albumin excretion, loss of glomerular filtration rate (GFR), and diabetic glomerular lesions." (PMID 34461808, 2021). "Low albumin, elevated BMI, tobacco use, and diabetes are associated with increased risk of postoperative infection, readmission, any complication, and mortality after primary THA." (PMID 34277906, 2021).